ERBB2 (erb-b2 receptor tyrosine kinase 2)
Diseases named in the same sentence as ERBB2 in open-access papers (continued):
Sharing a sentence is not in itself a finding about the gene and the disease.
tumor (continued). "Further, lymph node-positive patients whose tumours had both LOH for D17S5 and erbB-2 gene amplification had a higher risk of recurrence than patients whose tumours had neither of these genetic alterations." (PMID 7908218, 1994). "Furthermore, metabolites secreted by Lactobacillus casei, Lactobacillus paracasei, Lactobacillus rhamnosus, and Lactobacillus plantarum have been found to inhibit the expression of ErbB-2 and ErbB-3 genes, which subsequently decreases tumor proliferation mediated by these receptors." (PMID 39948481, 2025). "Unlike primary tumor cells, tumor cells in brain metastases may harbor mutations in genes such as ERBB2, BRAF, MYC, and BRCA2." (PMID 39780275, 2025). "However, detection of ERBB2 on liquid biopsy was at least in part dependent on tumor burden." (PMID 40512191, 2025). "Similarly, ERBB2 gene amplification throughout the tumor may confers resistance to EGFR-targeted monoclonal antibodies in CRC." (PMID 40828885, 2025). "However, we also observed several druggable pathway alterations in the tumor‐informed ctDNA group, such as ERBB2, MMR, and mTOR signaling, suggesting that alternative strategies beyond immunotherapy might be considered." (PMID 41287887, 2025). "We next aimed to investigate whether the anti-tumor effect of ERBB2 inhibition is T cell dependent." (PMID 41361170, 2025). "Furthermore, this tumor also carried a PIK3CA mutation and ERBB2 (HER2) amplification." (PMID 41230344, 2025). "Furthermore, we attempted to decipher molecular mechanisms of ERBB2 i14e in tumor cell growth." (PMID 39948369, 2025). "Finally, given the nature of the NCDB, there is no central pathology review, and the heterogeneity of ERBB2 expression within a tumor and interobserver variability may have led to misclassification of ERBB2 status." (PMID 40498483, 2025). "Moreover, RAB17 expression was strongly correlated with tumor stage, histological grade, time of last pregnancy, erb-b2 receptor tyrosine kinase 2 (ERBB2) expression, estrogen receptor (ER) levels, progesterone receptor (PR) levels, and the Ki67 index in patients with EC." (PMID 39242574, 2024). "Tumors with high ERBB2/CEP17 copy number ratio (≥6) had significantly greater cellular heterogeneity than ones with low (<6) in the pretreatment but not the posttreatment setting, suggesting that T-DM1+P treatment may preferentially target tumor cells with higher ERBB2 copy number gain." (PMID 38300710, 2024). "However, in our study larger tumor size was independently associated with high nodal burden in the luminal ERBB2-negative but not the ILC subgroup." (PMID 39320882, 2024). "The use of a paired study design allowed us to develop a prediction strategy that was independent of all markers currently used in the clinic, identifying ultralow and low‐risk patients with ER negative, ERBB2 positive tumors and tumor diameters larger than 2 cm." (PMID 38676390, 2024). "However, it is unclear whether there is a biologic interaction between TILs and the tumor cells that have varying degrees of ERBB2 protein, or they each play an independent role in the outcome through different mechanisms." (PMID 38517439, 2024). "Our NGS cut-off for ERBB2 amplification is set at >4 copies (Minimum Ploidy Gain, 5% CI >4), and taking tumor contents and intratumoral heterogeneity into consideration, lowering the cut-off to ≥3 copies could potentially improve the concordance rate from 76.1% to 88.0%." (PMID 38893219, 2024). "One of the rare but clinically especially aggressive variants is the “triple-negative” subtype, i.e. where the tumor cells do not express 3 receptors commonly targeted in hormonal and immunotherapy: estrogen receptor, progesterone receptor, and ERBB2 (HER2) receptor." (PMID 38560553, 2024).
tumor (continued). "While most target proteins on solid cancer cells are also expressed by healthy cells, such as ErbB2, the binding domain was re-engineered in favor of a low affinity to reduce the binding to the low antigen expressing healthy cells and finally to reduce the on-target off-tumor toxicity." (PMID 36672182, 2023). "Indeed, in the presence of picomolar concentrations of ErbB2-specific target modules both UniCARs efficiently redirected the NK cells to tumor targets expressing high or more moderate levels of ErbB2 on their surface, without affecting ErbB2-negative and otherwise NK-resistant cancer cells." (PMID 36688995, 2023). "In addition to mAbs, peptide–drug conjugates (PDCs) with lengths of less than 20 amino acids have been found to improve tumor targeting through the recognition of proteins that are overexpressed on tumor cell surfaces (erbB2, VEGF receptor, αVβ3 integrin, etc.)." (PMID 36839846, 2023). "However, determining ERBB2 overexpression using IHC staining of tumor tissues requires performing a biopsy, and findings may be erroneous because of observer variability and non-standardized IHC assays and scoring systems." (PMID 37174100, 2023). "Indeed, HER2 heterogeneity, defined as an area with ERBB2 amplification in > 5% but < 50% of tumor cells, or a HER2-negative area by FISH, showed complete response rates of 0% versus 55% in the non-heterogeneous subgroup with neoadjuvant therapy combining T-DM1 and pertuzumab." (PMID 36966267, 2023). "Therefore, in this study, the SNP in ERBB2 may be an important genetic alteration that promotes tumor angiogenesis and is manifested as an increased vascular index on Microvascular US." (PMID 37120792, 2023). "The ErbB2-antigen is targetable with vaccines that potentially trigger high levels of antibodies, which, through the mediation of lymphocyte T cells, elicits the suppression of the Th-1 response and T-cell cytotoxic proliferation in overexpressed tumor-antigens." (PMID 37686612, 2023). "Therefore, we hypothesized that tumor-supportive macrophages genetically engineered in situ with an ErbB2-specific CAR could exhibit enhanced phagocytic activity against cancerous BSG cells and subsequently initiate locoregional antitumor immunity." (PMID 36805678, 2023). "Moreover, HER2-AdVST (ERBB2 chimeric antigen receptor-modified adenovirus-specific cytotoxic T lymphocytes) joined to an intra-tumor injection of CAdVEC (an oncolytic adenovirus that helps the immune system) is being evaluated in an ongoing clinical trial (NCT03740256)." (PMID 35954382, 2022). "Furthermore, tumor ERBB2 ploidy was inferred from plasma QASeq results and was compared with FISH." (PMID 35379811, 2022). "In early disease, prospective clinical trials could select patients with HER2DX low-risk disease, HER2DX ERBB2 mRNA-high and HER2DX pCR-high tumours and demonstrate that trastuzumab-pertuzumab treatment without chemotherapy achieves outstanding long-term survival outcomes." (PMID 36374768, 2022). "In one patient with ERBB2 amplification detected in ctDNA following the development of resistance to platinum chemotherapy, treatment was changed to trastuzumab with reduced dose carboplatin and dose-dense paclitaxel, with significant tumour shrinkage and complete normalization of CA-125 achieved." (PMID 35545786, 2022). "They found that high expression levels of ERBB2 occurred in spheres showing hyperactive PI3K/AKT pathway and proved that triple targeting of ERBB2, MEK and PI3K induces CSC death and regression of anti-EGFR-resistant tumor xenografts, including those carrying KRAS and PIK3CA mutation." (PMID 35582524, 2022).
tumor (continued). "Interestingly, the inhibitory effect of the peptide was observed to be most striking in spheroids that over-expressed ERBB2 (HER2/neu), which suggests that tumours overexpressing HER2 might be more amenable to therapeutic intervention." (PMID 35568736, 2022). "In addition, HER2 immunohistochemistry (IHC) was carried out to evaluate whether the ERBB2 amplification was correlated to HER2 protein expression levels on the membrane of tumor cells." (PMID 36476508, 2022). "Whether or not ERBB2 mutation impacts on tumor cell proliferation in early ILC treated with preoperative endocrine therapy has not yet been investigated in this context." (PMID 35842479, 2022). "It has been reported that the overexpression of Erb-B2 Receptor Tyrosine Kinase 2 (ERBB2), mutations of EGFR/PI3K pathway, or the loss of Phosphatase and Tensin Homolog (PTEN), as well as mutations or amplification of AKT itself can result in increased PI3K-AKT signaling in tumor cells." (PMID 36434592, 2022). "Notably, in the invasive tumors caused by ERBB2 and ERBB3, THE insulin-like growth factor 2 (IGF2) and insulin-like growth factor binding protein 5 (IGFBP-5) are highly expressed, and these growth factors are very important for tumor growth." (PMID 35990843, 2022). "However, only double targeting of EGFR and ERBB2 led to durable tumor regression." (PMID 35582524, 2022). "Moreover, NRF2 silencing induces tumour growth retardation in mouse xenografts and a significant decrease in ErbB2 expression, a member of the human epidermal growth factor (EGF) receptor family that plays an essential role in cell proliferation and differentiation." (PMID 35453348, 2022). "Furthermore, follow-up CT scans showed SD until the patient quit therapy, which suggested that the combination therapy of afatinib and bevacizumab could inhibit the tumor growth in EGFR-mutant patients with ERBB2 amplification." (PMID 33663050, 2021). "Importantly, repeating this analysis with the keratinocyte and ERBB2 pathway-associated genes excluded resulted in the same clustering pattern, confirming that the pattern of expression of WNT-associated genes does distinguish between the tumour classes." (PMID 34003256, 2021). "Since both UICC tumor stage and the presence of focal amplifications are contributing factors to patient survival, we assumed that there might be some connection between the presence of the ERBB2 focal amplifications and GCA stage." (PMID 34764264, 2021). "Importantly, the interaction of DEPTOR with ErbB2 enhances the functions of ErbB2 in cell proliferation and survival, which implies that DEPTOR might promote ErbB2-mediated breast tumorigenesis and have oncogenic characteristics." (PMID 33995662, 2021). "As previously reported, multiplex sequencing of tumour samples from patients with gastroesophageal cancer is feasible and does identify potentially actionable targets, in most cases amplification of known oncogenes such as ERBB2, EGFR, FGFR1–3, KRAS and MET, in a significant proportion of patients." (PMID 34794033, 2021). "Based on these results, we demonstrated a new mechanism of CD151-mediated tumor progression by targeting EGFR/ErbB2 signaling pathway, by which CD151 promotes NSCLC proliferation, migration, and invasion, which may considered as a potential target of NSCLC treatment." (PMID 34108040, 2021). "Tumor tissue collected by re-biopsy was analyzed by next generation sequencing with an OncoAim Lung cancer targeting gene detection kit (Singlera Genomics, Inc., Shanghai, China) and revealed an acquired ERBB2 amplification (ERBB2_amp) in conjunction with EGFR 19 deletion mutation." (PMID 33663050, 2021).
tumor (continued). "As such, the PIDDosome should exert tumor‐suppressive functions that may explain observations of increased rates of tumor formation in mice lacking caspase‐2, challenged by oncogenic drivers such as MYC or ERBB2, or concomitant ATM loss." (PMID 33225610, 2020). "In addition, BLI confirmed sustained inhibition of tumor engraftment in all ERBB2-CAR CIK cell-treated mice (n = 8), whereas mice treated with WT CIK cells only transiently responded, but ultimately progressed in 2 of 6 (33%) cases (WT, n = 6 and ERBB2-CAR CIK, n = 8)." (PMID 33193388, 2020). "However, T-DM1 treatment, compared with CL, reduced the risk of PD to a similar degree regardless of tumor ERBB2 mRNA levels and tests for interaction between treatment and ERBB2 mRNA levels were not statistically significant (p = 0.07)." (PMID 32674482, 2020). "However, increasing the activity of these regulators to enhance AChR clustering could lead to tumor development as many of them, such as ErbB2 and mitogen-activated protein kinase/extracellular-signal-regulated-kinase, play an important role in cell growth." (PMID 31831571, 2020). "Moreover, GB-specific Abs were detected in ErbB2 CAR-NK cells-treated mice suggesting that the released cytokine may trigger a specific anti-tumor immunity." (PMID 32707982, 2020). "Moreover, a quantitative method as ERBB2 mRNA expression might recapitulate tumor heterogeneity in a single, easily manageable assay." (PMID 32674482, 2020). "High tumor BVD was observed in 43 of 82 patients (52%) and, compared with low tumor BVD, was associated with 4-IHC luminal-B (28% vs 10%, P = .02), whereas low BVD compared with high BVD was associated with ERBB2 overexpression (33% vs 7%, P = .003) (eTable 3 in the Supplement)." (PMID 33107920, 2020). "Beyond that, lack of specificity is assumed for diverse TKIs including erlotinib and gefitinib, suggesting putative further targets of strong homology such as ERBB2/HER2 which might be especially noticeable in the pool of p-SCC cells derived from a tumor with heterogeneous EGFR expression." (PMID 32978523, 2020). "Additionally, ERBB2 and keratin 17 (KRT17) were found to locate in the same chromosome region, which might have the following tumor associations." (PMID 33133157, 2020). "The misclassification was mainly between luminal A & B classes since they are two inherently similar tumor subtypes; or in the Her2 class due to limited information captured by expression profiles since it is defined as the gain in DNA copy number and/or over-expression of the ERBB2 gene." (PMID 32241303, 2020). "BID played a similar role by activating BAX/BAK 25 and ERBB2, also known as HER2, was a member of the human epidermal growth factor receptor family, promoting cell proliferation, survival, and playing an important role in the occurrence and development of tumor." (PMID 32780567, 2020). "Additionally, a selective pharmacological RANKL inhibitor could decrease tumor development and metastasis in ERBB2-positive context." (PMID 31796128, 2019). "Also, it is reasonable to conclude that combinatorial targeting of ERBB2 and RANKL could be a more effective approach, which would overcome RANKL effect in suppressing anti-tumor action of anti-ERBB2 agents." (PMID 31796128, 2019). "We examined whether high PD-L1 expression, tumor mutational burden (TMB), and presence of targetable mutations (EGFR, BRAF, ERBB2, RET or ALK translocations, ROS1 rearrangements) occur at different frequencies in tumors from black patients compared to non-black patients." (PMID 31645901, 2019). "In addition, major oncoproteins such as Ras and ErbB2 block tumor cell anoikis." (PMID 30545388, 2018). "Careful selection of the target antigen is one of the key factors in CAR T-cell-based immunotherapy strategies as targeting molecules on solid tumors that are not strictly tumor specific may retain significant potential for on-target, off-tumor toxicities, such as ERBB2/ HER2." (PMID 29975720, 2018).
tumor (continued). "The most frequently mutated genes across all tumor types included KRAS (30 patients), PIK3CA (16 patients), BRAF (6 patients), EGFR (5 patients), NRAS (4 patients) and ERBB2 (3 patients) whereas CCND1, ERBB2, EGFR and MYC were the genes most frequently subjected to copy number gain." (PMID 29854313, 2018). "If the tumour is low grade, node-negative and estrogen-receptor positive, hormone therapy may be recommended, however, if the tumour is of high grade and/or node-positive, chemotherapy is generally administered prior to targeted therapies depending on the hormonal/ErBb2 status of the tumour." (PMID 29304770, 2018). "Thus, at least under the conditions of in vitro assays, the mitigating effect of p140Cap on ERBB2 tumour growth could be correlated with the re-enactment by p140Cap of the differentiation program disrupted by ERBB2." (PMID 28300085, 2017). "The strong association between ERBB2 and ERBB3 overexpression in Uro and GU HER-positive cases, but not in the Basal/SCC-like HER2-positive cases, should also be considered, as ERBB3 has been shown to be essential for ERBB2 driven tumor formation and maintenance." (PMID 28388586, 2017). "The authors suggested the unbalanced allele transcription in ERBB2-negative tumours may be due to epigenetic mechanisms, whereby methylation silences a particular allele." (PMID 29259341, 2017). "Thus, H2-18 may be a more potent antitumor drug than trastuzumab plus pertuaumzb in ErbB2-amplified tumor that was acquired resistant to trastuzumab." (PMID 28514745, 2017). "In addition, we suggest that the p116/p185 ERBB2 ratio could be of help in the assessment of response to GA derivatives in tumor-derived organoids." (PMID 27863425, 2016). "Although some bigenic tumors (21 %) did show features of MMTV-IRS2 mouse tumors such as squamous differentiation, most bigenic tumors recapitulated ErbB2 tumor phenotypes, suggesting that the ErbB2 pathway may be the primary driver of tumorigenesis in these bigenic mice." (PMID 27765041, 2016). "In tumor cells with a high number of ErbB2, inhibition of ErbB2 by pertuzumab may be incomplete." (PMID 27596216, 2016). "CTC enrichment combined with a RT–PCR technology could already be used for the identification of tumor-related markers (EpCAM,MUC1, and ERBB2), EMT-associated transcripts (PI3Kα (phosphatidylinositol 3-kinase alpha), Akt-2, or Twist1), or stem cell markers such as ALDH1 (aldehyde dehydrogenase 1)." (PMID 25398926, 2015). "As for possible associations between RAR splicing variants and tumor cell phenotype, in accordance with the cell-line data, the content of RARa3 is generally higher in Luminal, relative to TN cancers and HER2+ tumors with no co-amplification of the ERBB2 and RARA loci (Fig7A)." (PMID 25888236, 2015). "Based on the apparent relevance of ERBB2 and ESR1 mRNA levels in discriminating patients with low or high risk of relapse, we applied to our dataset the PAM50 subtype predictor, which identifies the HER2-enriched (HER2E) subtype as the tumor group most responsive to trastuzumab." (PMID 26334217, 2015). "Thus, ERBB2 plays an important role in tumour development and progression." (PMID 27919043, 2014). "Since loss of either Nedd9 or p130Cas/BCAR1 impairs growth of ErbB2 tumours, the full activation of crucial ErbB2 downstream effectors, such as Src and FAK, may require the co-expression of Nedd9 and p130Cas/BCAR1, suggesting that these two Cas proteins cooperate during early ErbB2 tumourigenesis." (PMID 25606587, 2014). "However, active immunization targeting ErbB2 might induce tumor growth inhibition more efficiently than passive immunotherapy based on the generation of an extended memory immune response." (PMID 24886178, 2014).